TRBV30 (T cell receptor beta variable 30)
Description:
V region of the variable domain of T cell receptor (TR) beta chain that participates in the antigen recognition. Alpha-beta T cell receptors are antigen specific receptors which are essential to the immune response and are present on the cell surface of T lymphocytes. Recognize peptide-major histocompatibility (MH) (pMH) complexes that are displayed by antigen presenting cells (APC), a prerequisite for efficient T cell adaptive immunity against pathogens. Binding of alpha-beta TR to pMH complex initiates TR-CD3 clustering on the cell surface and intracellular activation of LCK that phosphorylates the ITAM motifs of CD3G, CD3D, CD3E and CD247 enabling the recruitment of ZAP70. In turn ZAP70 phosphorylates LAT, which recruits numerous signaling molecules to form the LAT signalosome. The LAT signalosome propagates signal branching to three major signaling pathways, the calcium, the mitogen-activated protein kinase (MAPK) kinase and the nuclear factor NF-kappa-B (NF-kB) pathways, leading to the mobilization of transcription factors that are critical for gene expression and essential for T cell growth and differentiation. The T cell repertoire is generated in the thymus, by V-(D)-J rearrangement. This repertoire is then shaped by intrathymic selection events to generate a peripheral T cell pool of self-MH restricted, non-autoaggressive T cells. Post-thymic interaction of alpha-beta TR with the pMH complexes shapes TR structural and functional avidity.
Synonyms: TCRBV20S1A1N2; TCRBV30S1
Gene: T-cell receptor variable (V) gene on chromosome 7 (142,812,586 to 142,813,399, reverse strand). Ensembl gene ENSG00000237254.
Subcellular location: Cell membrane
Gene Ontology:
Biological process: cell surface receptor signaling pathway
Cellular component: plasma membrane
Homologues: Orthologues: rabbit TRBV30 (77% identical), pig TRBV30 (75% identical), dog TRBV30 (71% identical), mouse Trbv31 (68% identical). Paralogues in human: TRBV7-2 (33% identical), TRBV7-3 (32% identical), TRBV7-4 (32% identical), TRBV7-9 (32% identical), TRBV10-3 (32% identical), TRBV19 (32% identical), TRBV4-2 (32% identical), TRBV7-6 (32% identical), TRBV9 (32% identical), TRBV14 (31% identical), TRBV18 (31% identical), TRBV25-1 (31% identical), and 39 more.
Diseases named in the same sentence as TRBV30 in open-access papers:
TRBV30 is named in the same sentence as 7 diseases in open-access papers, as found by Europe PMC text mining. Sharing a sentence is not in itself a finding about the gene and the disease. The quoted sentences say what the papers report.
infection (2 papers, 2020 to 2023). The state of being infected such as from the introduction of a foreign agent such as serum, vaccine, antigenic substance or organism. "There were minor differences between the V-gene usage of the two infection cohorts in both spleen/LN and lungs, and in fact, we even noticed a single V-gene, TRBV30, that was upregulated in chronic infection relative to acute infection in both spleen/LN and lung repertoires." (PMID 32547546, 2020).
tumor (1 paper, 2022). "The tumor group has a significantly lower gene usage of TRBV30, TRBV12-4, TRBV4-1, TRBV4-2, TRBV18, TRBJ1-1, TRBJ1-5, and TRBJ2-2." (PMID 35967453, 2022).
TRBV30 also shares sentences with these, for which no sentence is quoted: acute myocardial infarction (1 paper); asthma (1); cancer (1); colorectal cancer (1); systemic lupus erythematosus (1).